ALB (albumin)
Diseases named in the same sentence as ALB in open-access papers (continued):
Sharing a sentence is not in itself a finding about the gene and the disease.
Hypertension (continued). "Our results revealed that the DKD group had significantly higher values for age, annual household income under $20,000, hypertension, cardiovascular disease, WC, GGT, glycohemoglobin, FPG, TG, BUN, SUA, Scr, urinary albumin and UACR compared to the non-DKD group (P<0.05)." (PMID 38559695, 2024). "Patients with higher serum albumin levels were younger, male, had a slightly higher BMI, higher BI scores, lower NIHSS scores, had a history of hypertension, no history of coronary heart disease and atrial fibrillation, were non-smokers, and had atherosclerosis according to the TOAST classification." (PMID 39835151, 2024). "On multivariate analysis, hypertension (p=0.024), no recent SACT (p=0.017), hematological malignancy (p=0.029), low albumin (p≤0.001), leucocytosis (p=0.002) and lymphocyte count < 500/μl (p=0.004), correlated with mortality within six months of COVID-19 infection." (PMID 38288187, 2023). "The six-month mortality rate in patients with active cancer was significantly higher in patients with hypertension (p=0.024), no recent SACT (0.017), hematological cancer (p=0.029), low albumin (p=<0.001), leucocytosis (p=0.002) and lymphocyte count of less than 500/μL (p=0.004)." (PMID 38288187, 2023). "In quartile 4, participants had higher neutrophil and lymphocyte counts, lower Cr levels, higher TG, TC, and albumin levels, and were more likely to have never smoked, engage in intermediate‐intensity physical activity, be light drinkers, have no CVD, and have no hypertension." (PMID 38455180, 2023). "The γ-glutamyl transpeptidase (GGT), blood urea nitrogen (BUN), albumin/globulin (A/G), Ca, Mg, lactate dehydrogenase (LDH), and α-hydroxybutyric-dehydrogenase (α-HBD) levels in COVID-19 patients with hypertension were higher than in COVID-19 patients without hypertension." (PMID 36326681, 2022). "There was a significantly negative correlation between the log2 UACR levels and ALB (P=0.003), while significantly positive correlation was observed between log2 UACR and HbA1c (P < 0.001), independent of hypertension, the use of ACEI or ARB medication, smoking, age, and gender." (PMID 32076606, 2020). "Moreover, we report that HbA1c level had a positive correlation with UACR, independent of hypertension, even in T2DM patients with a normal range of UACR, which suggested that there are some mechanisms between glycemic control and urinary albumin excretion." (PMID 32076606, 2020). "Therefore, the present study was designed to evaluate the relationship between serum albumin levels and 24-h ABPM recordings in non-diabetic essential hypertensive patients." (PMID 27276394, 2016). "Among T2DM patients with normal urine albumin excretion (<30 mg/24 h) and preserved GFR, RAAS blockade has been demonstrated to prevent the development of albuminuria in the presence of hypertension, although not without hypertension." (PMID 26569322, 2015). "In conclusion, our results showed that the detection of both urinary albumin concentration and also estimation of UACR in single urine sample is accurate and cost-benefit procedure to identify microalbuminuric subjects regardless of hypertension state." (PMID 24455207, 2013). "Background/Objective: The C-reactive protein-to-albumin ratio (CAR) reflects both systemic inflammation and nutritional status and has been proposed as a prognostic marker in critical illness, yet its value in intensive care unit (ICU) patients with pre-existing hypertension is not well defined." (PMID 42194645, 2026). "However, the PDW-to-serum albumin ratio (PAR) has not been evaluated in any disease population, and whether the PAR could be a prognostic marker in hypertension remains unknown." (PMID 40593009, 2025).
chronic kidney disease (892 papers, 2005 to 2026). Impairment of the renal function secondary to chronic kidney damage persisting for three or more months. "Diabetic nephropathy (DN), indicated by persistent urinary albumin excretion or albuminuria, is the major cause of end stage renal disease worldwide." (PMID 42310331, 2026). "Chronic kidney disease was associated with an increased risk (HR 1.63, 95% CI: 1.02–2.59, p = 0.040), while higher preoperative serum albumin levels were protective (HR 0.43, 95% CI: 0.26–0.71, p < 0.001)." (PMID 40943953, 2025). "Clinically, even mild elevations in urinary albumin are associated with accelerated progression of chronic kidney disease (CKD) and increased risk of adverse cardiovascular outcomes." (PMID 41264588, 2025). "Univariate analysis showed that a high NLR, a low albumin concentration (<3.5 g/dL), cerebrovascular disease, end-stage renal disease, and CLTI were significantly associated with 5-year mortality." (PMID 39797294, 2025). "The estimated glomerular filtration rate (eGFR) and urine albumin level are readily available clinical parameters that are currently used to identify the risk of chronic kidney disease progression." (PMID 40046921, 2025). "Diabetic kidney disease (DKD), characterized by a progressive decline in estimated glomerular filtration rate (eGFR) and/or elevated urinary albumin excretion, is strongly associated with increased risks of end-stage renal disease and cardiovascular mortality." (PMID 40860624, 2025). "While urinary protein excretion improves postpartum, the ongoing damage to the endothelial glycocalyx and podocytes continues to contribute to low-level albumin excretion, raising the long-term risk of chronic kidney disease in women with preeclampsia." (PMID 39857389, 2025). "Protein-energy wasting (PEW), characterized by low levels of serum albumin or prealbumin, muscle loss, and weight reduction, is a common and highly predictable indicator of poor prognosis in patients with chronic kidney disease." (PMID 39940308, 2025). "Similar correlations between body mass and urine protein have been observed in human medicine, where body mass index is associated with total urine protein and albumin excretion, and obesity is a risk factor for proteinuria and end-stage renal disease." (PMID 40041720, 2025). "Currently, the baseline estimated glomerular filtration rate (eGFR), the urine albumin level and renal fibrosis are the common risk and prognostic factors for chronic kidney disease (CKD)." (PMID 40046921, 2025). "In this review, we summarized that hypertension, diabetes, hypoproteinemia (serum albumin <30g/L), anemia, autoimmune diseases, extrarenal irAEs, and chronic kidney disease (CKD) are all associated with the higher risk of ICI-AKI." (PMID 38464524, 2024). "Patients with a higher albumin/creatinine or protein/creatinine ratio in urine are at greater risk of developing end-stage renal disease, according to risk calculators developed for the North American population." (PMID 38498672, 2024). "According to the Cox proportional hazards model conducted by Seliger and colleagues, a 1-g/dL decrease in the serum albumin concentration was associated with a 43% increased risk of stroke among patients with end-stage renal disease." (PMID 39239394, 2024). "Several studies show that changes in serum albumin during hospital stay are associated with poor outcomes in various diseases, such as cancer, end-stage renal disease, cardiologic disease, and traumatic brain injury." (PMID 39518469, 2024). "For instance, a lower ALB/GLB ratio is associated with poorer outcomes in patients with certain cancers or chronic kidney diseases." (PMID 37752439, 2023). "A recent systematic review analyzed albumin concentration and found that chronic kidney disease patients with periodontitis presented lower albumin levels, indicating that their health was at risk." (PMID 37047877, 2023).
chronic kidney disease (continued). "The last marker studied was albumin, a well-established diagnostic and prognostic marker for assessing the degree of glomerular disease severity in the progression of chronic kidney disease." (PMID 36835210, 2023). "Meanwhile, another parallel evidence shows urinary Cu concentration was strongly positively associated with urinary albumin/creatinine ratio, which was a sensitive indicator of chronic kidney disease (CKD)." (PMID 35923200, 2022). "Of note, patients with chronic kidney disease estimated with CKD-EPI-CysC had lower levels of albumin (34.1 g/L versus 38.05 g/L; P=0.0137), a risk factor associated to MM." (PMID 35469191, 2022). "Studies involving the association of blood albumin with prognosis in patients with chronic kidney disease (CKD) during intensive care unit (ICU) were scarce." (PMID 35850629, 2022). "Chronic kidney disease–related risk factors like albumin-to-creatinine ratio, albuminuria (normal, micro, macro), urine creatinine, and estimated glomerular filtration rate (eGFR) act as positive or negative risk factors in different subcohorts." (PMID 36051323, 2022). "Hazard ratios (HRs) of chronic kidney disease risk progression according to baseline urinary albumin/creatinine ratio quartiles followed for a mean 4.9 ± 4.0 years (N=4821)." (PMID 35721762, 2022). "Subtle changes in albumin excretion reflect generalized vascular processes and highlight the complex association between chronic kidney disease and cardiovascular disease." (PMID 35858835, 2022). "Studies of aging Munich Wistar Frömter rats, a model of spontaneous albuminuric chronic kidney disease, revealed that extensive loss of endothelial glycocalyx correlates with defects in microvascular permeability to albumin." (PMID 35746884, 2022). "Serum albumin, known as an independent risk factor of mortality as well as a nutritional marker in end-stage renal disease (ESRD) patients, has been reported as lower in frail individuals than in healthy ones." (PMID 36271111, 2022). "As we know, low serum albumin is associated with high mortality in patients with end-stage renal disease (ESRD) on chronic dialysis." (PMID 35755025, 2022). "Some of the prior studies reported serum albumin was associated with chronic kidney disease and cardiovascular, which is also a risky factor for dysphagia in elderly hip fracture surgery patients." (PMID 35840689, 2022). "The overall rate of chronic kidney disease progression is relatively high, and low serum albumin and high albuminuria levels are associated with kidney failure progression in newly diagnosed diabetic patients." (PMID 34268015, 2021). "Comorbidities associated with low serum albumin levels such as cirrhosis, chronic kidney disease, end-stage renal disease, nephrotic syndrome, protein-losing enteropathy, and chronic protein-calorie malnutrition were not adjusted for in this article." (PMID 33725003, 2021). "Chronic kidney disease (OR = 14), C-reactive protein >100 IU/L (OR 6.964), and S. albumin <3 gm/dl (OR = 8) were detected to be risk factors for mortality in patients." (PMID 34285680, 2021). "The most widely-diagnosed condition related to urinary proteins is albuminuria—excessive amounts of albumin in urine (more than 30 mg/L) which is associated with chronic kidney disease, diabetes, acute kidney damage, etc.." (PMID 33917374, 2021). "Serum albumin <3.8 g/dL represents one of the clinical diagnostic criteria of protein energy wasting (PEW) in patients with chronic kidney disease (CKD)." (PMID 34233593, 2021). "Renal outcomes showed a significant lowering of risk of acute kidney failure, progression of chronic kidney disease, renal mortality, and improvement in urinary albumin creatinine ratio." (PMID 34650848, 2021). "Lower serum albumin has also been associated with worse LV diastolic dysfunction in children with chronic kidney disease." (PMID 32776978, 2020).
chronic kidney disease (continued). "Common causes of pleural effusion such as chronic kidney disease, congestive cardiac failure, critical illness, low albumin states, and active cancer states were identified and associated in patients with unilateral as well as bilateral pleural effusions." (PMID 33425521, 2020). "Because glomeruli filter blood, albumin is a good biomarker of chronic kidney disease (CKD) caused by glomerular abnormalities but is insufficient to determine subsequent prognosis." (PMID 32545899, 2020). "In the multivariate regression analysis, prevalent HF and VF, lower BMI and albumin level, and having chronic kidney disease or cancer were associated with higher mortality rates." (PMID 31300660, 2019). "Albuminuria is both a biomarker and risk factor in chronic kidney disease, and excessive albumin uptake in renal epithelial cells is accompanied by time- and dose-dependent activation of the mitochondrial apoptotic pathway." (PMID 30864838, 2019). "Patients with chronic kidney disease, cerebrovascular disease, cancer, advanced dementia, delirium, polypharmacy, weight loss history, functional dependency, pressure ulcers and low albumin levels were more likely to die over the course of follow-up." (PMID 29694607, 2018). "This retrospective cohort study of 1,352 participants with biopsy-proven IgAN determined the associations between serum albumin level and the incidence of end-stage renal disease (ESRD) using a Cox proportional hazards model." (PMID 29795559, 2018). "A few clinical studies have shown an association between low serum albumin and the progression of chronic kidney disease." (PMID 29795559, 2018). "The foremost complication associated with T2D is chronic renal failure which is commonly screened for in the clinical setting by measuring urine and plasma protein levels, namely microalbumin, creatinine and albumin-creatinine ratio (ACR)." (PMID 27402965, 2016). "Studies have suggested that a serum albumin level of less than 3.8 g/dL (and/or a reduction in serum albumin levels) confers a greater mortality risk in patients with end-stage renal disease (ESRD) and in various other disease states." (PMID 24499139, 2013). "It is already know that even patients with high-normal albumin excretion rate are at high-risk of developing chronic renal failure." (PMID 24265821, 2013). "Serum albumin is widely recognized as a biomarker of underlying inflammation and nutritional status in patients with chronic kidney disease, but it is also correlated with age, proteinuria, and hemoglobin levels." (PMID 23983784, 2013). "Reductions in blood pressure (BP) and urinary albumin excretion in chronic kidney disease (CKD) have been shown to reduce the risk of cardiovascular (CV) events and improve renal outcome." (PMID 22073219, 2011). "Similar to prior papers, we identified several risk factors associated with VRE acquisition including end-stage renal disease, active wounds, and low serum albumin levels." (PMID 21914221, 2011). "While many women experience a rapid decline in protein and albumin excretion post-childbirth, some may retain residual proteinuria, indicating a potential risk for future chronic kidney disease." (PMID 39857389, 2025). "This study aims to develop and externally validate a scoring nomogram based on three key indicators (Peritoneal dialysis vintage, age, and albumin) to predict the risk of developing abdominal wall hernia in patients with end-stage renal disease (ESRD) undergoing peritoneal dialysis." (PMID 41446859, 2025). "Chronic kidney disease may be associated with chronic inflammation, which may aggravate the cancer-induced inflammatory status and often low serum albumin levels due to urinary loss." (PMID 41514593, 2025).
chronic kidney disease (continued). "The univariable analysis identified the following factors as significantly related to a higher risk of death: higher stage of chronic kidney disease (>G2: HR = 2.08; p = 0.0153), low albumin levels (HR = 2.68; p = 0.0007), and high creatinine levels (HR = 2.04; p = 0.0182)." (PMID 38610941, 2024). "Several studies reported the positive association of an elevated serum urea-to-albumin ratio with increased mortality in critically ill patients with non-chronic kidney diseases, septic shock and community-acquired pneumonia; however, heterogenous cut-off levels have been described." (PMID 37240644, 2023). "Improvements in physical health and fatigue associated with increased albumin concentration may exacerbate discontent with the limitations imposed on daily living by the diagnosis of advanced chronic kidney disease, leading to lower emotional well-being." (PMID 37158906, 2023). "Every 30% reduction of urinary albumin might the decreased by 23.7% (95%CI 11.4–34.2%) for risk of end-stage renal disease." (PMID 36740710, 2023). "Serum ALB serves as an established and risk-adjusted predictor of progression to end-stage renal disease (ESRD) and all-cause mortality in patients with chronic kidney disease (CKD), especially in more vulnerable populations, such as HIV-infected and elderly adults." (PMID 37762957, 2023). "Additionally, there was a second-highest risk group for end-stage renal disease that was missed by creatinine alone but detected by cystatin C and the albumin–creatinine ratio." (PMID 37509111, 2023). "In addition to enhanced hepatic synthesis in response to peritoneal albumin loss, another presumed mechanism of elevation in prealbumin level in chronic renal failure is the impairment in degradation by renal tubules." (PMID 36346823, 2022). "Chronic kidney disease, characterized by a reduced glomerular filtration rate (GFR) and/or increased urinary albumin excretion, is an increasing public health issue owing to its high prevalence and increased risk of end-stage renal disease, cardiovascular disease, and premature death." (PMID 34025408, 2021). "Additionally, reduced level of circulating albumin, due to decreased production in the liver or increased loss in the kidney, is common in patients with end-stage renal disease." (PMID 34285713, 2021). "The use of albumin excretion has been well established as a diagnostic and prognostic marker to evaluate the degree of severity of glomerular diseases in the progression of chronic kidney disease." (PMID 34768464, 2021). "In our study, logistic regression analysis indicated that chronic kidney disease, C-reactive protein >100 IU/L, and serum albumin <3 gm/dl were independent risk factors associated with mortality in melioidosis patients–(OR = 14.0, OR = 6.964, and OR = 8.0, respectively)." (PMID 34285680, 2021). "Age, chronic kidney disease, and low albumin levels increase the risk of mortality." (PMID 30606164, 2019). "We assumed that prodromal renal hyper-filtration and increased glomerular pressure in the early stage of chronic kidney disease could be the cause of increased urinary albumin in the present study." (PMID 31590639, 2019). "Our data advance the understanding of the cell signaling pathways responsible for albumin-induced podocyte apoptosis and may contribute to the development of preventive and therapeutic strategies for albuminuria-associated chronic kidney diseases (CKD)." (PMID 30573754, 2018). "Association of plasma potassium with risk of developing chronic kidney disease defined as eGFRcreatinine-cystatin C <60 ml/min/1.73m2 or urinary albumin excretion >30 mg/24h in 5,130 participants of the Prevention of Renal and Vascular End-Stage Disease (PREVEND) study." (PMID 28346526, 2017). "Serum albumin concentration was found to be an independent predictor of mortality risk in a broad range of clinical and research settings in adults, especially in those with end-stage renal disease." (PMID 26885251, 2016).